GAPDHP1 (glyceraldehyde-3-phosphate dehydrogenase pseudogene 1)
Synonyms: formerly GAPDP1; GAPDHL2; GAPDL2
Gene: Processed pseudogene on chromosome X (39,787,132 to 39,788,136, reverse strand). Ensembl gene ENSG00000228232.
Diseases named in the same sentence as GAPDHP1 in open-access papers:
GAPDHP1 is named in the same sentence as 1 disease in open-access papers, as found by Europe PMC text mining. Sharing a sentence is not in itself a finding about the gene and the disease. The quoted sentences say what the papers report.
cancer (1 paper, 2022). A tumor composed of atypical neoplastic, often pleomorphic cells that invade other tissues. "Meanwhile, SMYD2 and GAPDHP1 expression levels in cancer tissues were higher than in paracancerous tissues." (PMID 35498536, 2022). "In addition, quantitative real-time PCR results showed that the expression levels of ATP1A2, CILP, and THSD4 were downregulated and the expressions of SMYD2 and GAPDHP1 were upregulated in cancer tissues compared with normal tissues." (PMID 35498536, 2022). "Namely, the expression levels of ATP1A2, CILP, and THSD4 were downregulated in cancer tissues compared with paracancerous tissues, whereas the expression levels of SMYD2 and GAPDHP1 were upregulated." (PMID 35498536, 2022).